SMC4 (structural maintenance of chromosomes 4)
Diseases named in the same sentence as SMC4 in open-access papers (continued):
Sharing a sentence is not in itself a finding about the gene and the disease.
cystic fibrosis (1 paper, 2017). Autosomal recessive disorder caused by pathogenic variants in the CFTR gene (cystic fibrosis transmembrane conductance regulator), which encodes a chloride and bicarbonate channel expressed in epithelial cells, and follow the diagnosis criteria. "Each of the phylogroups Smc1 to Smc4 currently holds ecologically coherent groups of strains: Smc1 and Smc2 contain exclusively Mexican river isolates recovered in this study, Smc3 groups cystic fibrosis isolates and Smc4 predominately rhizosphere isolates from diverse plants and parts of the world." (PMID 28861062, 2017).
fibrosarcoma (1 paper, 2020). A malignant mesenchymal fibroblastic neoplasm affecting the soft tissue and bone. "Also in the Detwiller datasets, SMC4 was overexpressed in fibrosarcoma, lieomyosarcoma, pleomorphic liposarcoma and malignant fibrous histiocytoma compared to normal samples (8.252-, 8.448-, 6.595- and 8.103-fold increases, respectively)." (PMID 33460400, 2020).
malaria (1 paper, 2020). Malaria is a serious and sometimes fatal disease caused by a parasite that commonly infects a certain type of mosquito which feeds on humans. "Here we describe the structure, localization, and functional role of the condensin core subunits (SMC2/SMC4) in the mouse malaria-causing parasite P. berghei using MD, live cell imaging, ChIP-seq, protein pull-down, and conditional gene knockdown approaches." (PMID 32049018, 2020).
melanoma (1 paper, 2022). A malignant, usually aggressive tumor composed of atypical, neoplastic melanocytes. "Diacylglycerol kinase (DGKB), TGc domain-containing protein (Tgm2), structural maintenance of chromosomes 4 (SMC4) and mastermind-like transcriptional coactivator 2 (MAML2) were related to lipid metabolism, facilitating melanoma development in the severe-EMN group." (PMID 35202347, 2022).
meningioma (1 paper, 2022). A generally slow growing tumor attached to the dura mater. "Along with other candidates also associated with WHO grades, such as SMC4 (three hits, NC) and PAX6 (four hits, PC), these genes may constitute other interesting progression biomarkers in meningiomas." (PMID 36551712, 2022). "Hence, the hypomethylation of SMC4 in high-grade meningiomas could likely lead to overexpression, which is consistent with previous data indicating poor prognosis in other tumors." (PMID 36551712, 2022).
metastatic prostate carcinoma (1 paper, 2025). A carcinoma that arises from the prostate gland and has spread to other anatomic sites. "Our findings indicate that outlier expression of SMC4 exhibit a robust prognostic association with metastatic progression, and that the SMC4 prognostic outlier genes continue to occupy roles in metastatic prostate cancer." (PMID 40278414, 2025). "The association between SMC4 and GLUT1 was confirmed by co‐IP, providing new insights into the mechanism underlying metastatic prostate cancer." (PMID 40278414, 2025).
ovarian tumors (1 paper, 2024). "Except for ATAD2, expression of other genes (ASF1B, CCNE1, CDC20, CDCA8, RECQL4, RNASEH2A, and SMC4) was upregulated in ovarian tumors compared to non-cancerous tissue." (PMID 39199556, 2024).
pancreatic ductal adenocarcinoma (1 paper, 2021). An infiltrating adenocarcinoma that arises from the epithelial cells of the pancreas. "High expression of SMC4 predicted worse prognosis of pancreatic ductal adenocarcinoma patients." (PMID 34403221, 2021).
psoriasis (1 paper, 2023). An autoimmune condition characterized by red, well-delineated plaques with silvery scales that are usually on the extensor surfaces and scalp. "SMC4 is an essential gene that encodes a member of a ubiquitous family of chromosome-associated ATPases, and ubiquitination is viewed as a key process in psoriasis pathology." (PMID 37035327, 2023). "The expression levels of phospholipid scramblase 1 (PLSCR1), heme binding protein 1 (HEBP1), structural maintenance of chromosomes 4 (SMC4), and RuvB like AAA ATPase 1 (RUVBL1) genes were shown to be reversed by candidate compounds for psoriasis using the RORUCI values." (PMID 37035327, 2023).
serous ovarian cancer (1 paper, 2024). "Additionally, the Kaplan–Meier plot results revealed that increased expression of ATAD2, CCNE1, CDC20, and SMC4 was associated with poor survival in serous ovarian cancer patients (p < 0.05)." (PMID 39199556, 2024).
Stroke (1 paper, 2012). Sudden impairment of blood flow to a part of the brain due to occlusion or rupture of an artery to the brain. "SMC4, NUF2 and ECT2 were augmented in the core and PI areas at 3 d after stroke." (PMID 23284893, 2012).
Werner syndrome (1 paper, 2023). "In Werner syndrome, transcriptional downregulation and DM-CpGs have been observed in SMC431, but the potential implication of DNAm changes in SMC4 in relation to TBD is so far unknown." (PMID 37193737, 2023).
tumor (39 papers, 2011 to 2025). "We found that GC patients with high DNA binding activities of SMARCA5 and E2F3 and high phosphorylation of CCNL1 (at T67) and SMC4 (at S41) in tumor tissues associated with poor prognoses (Log-rank test, p < 0.05)." (PMID 36788224, 2023). "We found that the expression level of SMC4 in tumor tissues is associated with the expression level of gene markers of tumor-infiltration immune cells including exhausted T cells, NK cells, Tfh, Treg, monocyte, TAM, B cell, T cell and neutrophils." (PMID 36719264, 2023). "Understanding the function of SMC4 in tumor progression will not only advance our knowledge of the mechanisms underlying tumor aggressiveness, but also establish SMC4 as a novel tumor prognostic marker or a potential therapeutic target for treating tumors." (PMID 37007153, 2023). "Recent studies demonstrated also that SMC4 is associated with tumor progression and invasion and the expression of SMC4 is positively correlated with HIF-1a30." (PMID 32753750, 2020). "The statistical analysis indicated that upregulated SMC4 protein was associated with WHO tumor grade (P<0.001) and vital status (P<0.001)." (PMID 28287612, 2017). "In summary, all of these indicate that SMC4 may be enormously associated with the occurrence, development, evolution, and prognosis of tumors and even become a new tumor prognostic marker and potential therapeutic target." (PMID 37007153, 2023). "SMC4 protein is associated with tumor development, and the main biological function of SMC4 protein is the involvement in the dynamic changes of higher-order chromosomal structures, such as chromosome condensation and separation, DNA recombination, and repair of DNA damage." (PMID 33563317, 2021). "SMC4, a core subunit of the condensin complex, orchestrates chromosome dynamics, DNA damage repair, and mitotic accuracy, thereby influencing tumor initiation and progression." (PMID 40933894, 2025). "SMC4 also regulates PGAM1 transcription, and dual loss of SMC4 and PGAM1 disrupts F‐actin assembly, causing cell division failure and polyploidy, ultimately suppressing tumour proliferation." (PMID 41020792, 2025). "SMC4 (structural maintenance of chromosomes 4) is closely related to the occurrence, progression, immune infiltration, and prognosis of various tumor types." (PMID 39548061, 2024). "The results showed that in a variety of tumor tissues, the expression level of SMC4 was significantly up-regulated." (PMID 36719264, 2023). "In conclusion, we revealed that compared with the normal tissues, the expression of SMC4 was significantly up-regulated in many malignant tumor tissues." (PMID 37007153, 2023). "Decreasing pattern of gene expression within the model associated with lower expression in the tumor and normal samples was found in genes such as TPX2 and SMC4." (PMID 37627150, 2023). "The expression level of SMC4 mRNA in different tumor tissues and normal tissues was detected using the ONCOMINE database and TIMER database." (PMID 36719264, 2023). "Next, cell viability assays were performed to explore the role of SMC4 knockdown on tumour proliferation of U87 and U373 cells." (PMID 35615996, 2022). "The results demonstrated that the proliferative capacity of tumour cells was significantly attenuated after SMC4 knockdown." (PMID 35615996, 2022). "Six genes were up-regulated in the tumor group and high-risk group consisting of SMAD3, CENPA, KIF23, NUSAP1, INCENP, and SMC4." (PMID 36401386, 2022). "High expression of SMC4 is related to tumor size, dedifferentiation, advanced stages, and vascular invasion of liver cancer." (PMID 34403221, 2021). "Consistent with this notion, it has been recently shown that Smc4 protein levels correlate with an aggressive phenotype in tumor cells, establishing a link between condensin levels and tumor progression in humans." (PMID 29949571, 2018).
tumor (continued). "Overexpression of structural maintenance of chromosomes 4 (SMC4) has been reported to be involved in tumor cell growth, migration and invasion, and to be correlated with poor prognosis of cancer patient." (PMID 28287612, 2017). "The microarray data analysis and cell experiments revealed that SMC4 is closely related to the tumor cell cycle, cell adhesion, and RNA processing." (PMID 27687868, 2016). "The tumor-promoting effect of SMC4 was determined by WST-1, soft agar colony formation, cell motility and invasion assays." (PMID 24980149, 2014). "Furthermore, altered immune cell infiltration, such as decreased activation of CD4 and CD8 T cells upon SMC4 inhibition, highlights the intricate balance between tumor cell death pathways and immune surveillance." (PMID 39949776, 2025). "Forced expression of SMC4 significantly upregulated LDHA protein levels, whereas SMC4 knockdown resulted in marked LDHA downregulation, suggesting SMC4 may regulate tumor energy metabolism." (PMID 40933894, 2025). "Elevated expression of SMC4 is related to the poor outcome of tumor patients." (PMID 36719264, 2023). "It is surprising to find that SMC4 may be a novel tumor prognostic marker and potential tumor therapeutic target." (PMID 37007153, 2023). "Furthermore, low expression levels of microRNA-124-5p can lead to a poor prognosis of CRC via targeting of SMC4, which further confirms the novel tumor prognostic marker and potential tumor therapeutic target role of SMC4 in CRC." (PMID 37007153, 2023). "This suggests that SMC4 plays a role in regulating the tumor immune infiltration of T helper cells." (PMID 36719264, 2023). "Similar to how normal somatic cells can replicate the gene expression patterns of embryonic cells to gain an edge over them, tumor cells with high SMC4 expression may do the same." (PMID 37007153, 2023). "In conclusion, we present this review which introduces the structure, biological function of SMC4, and its correlation with the tumor in detail; it might provide new insight into a novel tumor prognostic marker and potential tumor therapeutic target." (PMID 37007153, 2023). "Finally, a recent HotNet2 Pan-Cancer analysis suggested that multiple cancers harbor rare mutations in SMC2, SMC4, NCAPD2, NCAPD3, NCAPH2 and NCAPG2, supporting a tumor-suppressor role for condensin proteins." (PMID 36169232, 2022). "SMC2, SMC3, and SMC4 are also related to tumor purity and immune infiltration levels of HCC." (PMID 36281130, 2022). "SMC4 was found to be involved in tumor cell growth, migration, and invasion." (PMID 36551712, 2022). "Recent studies have unveiled its correlation with tumor proliferation, differentiation, and vascular invasion in different cancers and suggested that miR-219 might be responsible for the regulation of SMC4 expression." (PMID 34868977, 2021). "In the GEPIA database, SMC4 is dysregulated in 13 out of 32 types of malignant tumor tissues." (PMID 34868977, 2021). "Functional assays demonstrated that SMC4 could effectively promote tumor cell growth rate, colony formation in soft agar, wound-healing and invasion." (PMID 24980149, 2014). "Therefore, targeting SMC4 could theoretically synergize with anti-tumor drugs that induce DNA damage and disrupt the proliferation cycle of cancer cells, such as temozolomide and cisplatin." (PMID 40933894, 2025). "Additionally, SMC4 may influence the expression of chemokines or cytokines that attract or activate T cells within the tumor microenvironment." (PMID 39949776, 2025). "The ‘tumor cells 1’ cluster had the gene expression characteristic of stem-like tumor cells with an elevated expression of genes involved in cell division and chromosome segregation such as Top2a, Mki67, Cenpf, Cenpe, Incenp, Anln, Ccna2, Kif20b, Ccnb1, and Smc4." (PMID 39769061, 2024). "Likewise, tumor cells with high SMC4 expression may mimic the gene expression patterns of embryonic cells to enhance their competitive advantage over normal somatic cells." (PMID 37007153, 2023).
tumor (continued). "Therefore, we conclude that SMC4 can promote the tumor cell proliferation, invasion and migration." (PMID 24980149, 2014). "Cell cycle proteins were evaluated based on their altered expression patterns (WAPAL, AHCTF1, etc.), phosphorylation patterns (CCNL1 T67, SMC4 S41, etc.), and inferred TF activities (SMARCA5, E2F3, etc.)in GC tumor tissues." (PMID 36788224, 2023). "We found that increased expression of SMC2, SMC3, and SMC4 might play a significant role in HCC, and could be useful as molecular markers to identify high-risk patients, Our results also provide insights for further research of SMC family members as potential tumor therapeutic target in HCC." (PMID 36281130, 2022). "The expression level of SMC4 is highly variable in lung ADC, which is consistent with tumor heterogeneity." (PMID 27687868, 2016). "Regarding the top genes present in these terms, we found genes involved in carcinogenesis with potential prognostic and therapeutic roles in cancer (FBXO5 and SMC4) and also PRC1, whose deregulation is related to chromosomal instability and tumor heterogeneity." (PMID 35954157, 2022). "Of note, contrast to SMC4, the patients with NCAPH overexpression in colon cancerous tissues had a significantly better prognosis and survival rate than those with low-expression of NCAPH in tumor tissues." (PMID 34557090, 2021). "Also, SMC4 correlates with reducing OS and PFI in LGG patients despite the new tumor events status or histologic staging." (PMID 34868977, 2021). "In addition, consistent with previous research results, we also found that SMC1A, SMC1B, SMC2, SMC3, SMC4, and SMC6 were overexpressed at the mRNA level in HCC when compared with non-tumor cells." (PMID 34527684, 2021). "We further showed that expression of SMC4 may be useful for the early detection of HCC, and is related to the progression and invasion the tumor." (PMID 24980149, 2014). "In a re-analysis of those data, one prominentgene-expression feature included genes regulating the cell-cycle (e.g. CCNE1,CDK1, CDC25A), and involved in DNA replication(e.g. POLE2, MCM4, TK1) andchromosome dynamics (e.g. SMC4, CENPE), ostensiblyreflecting tumor cell proliferation levels." (PMID 21629784, 2011). "The results showed that SMC4 was strongly upregulated in 4 HCC cell lines compared to normal cells (L02), and highly expressed in 4 primary HCC samples compared to paracancerous and non-tumor samples." (PMID 24980149, 2014).
cancer (30 papers, 2012 to 2025). A tumor composed of atypical neoplastic, often pleomorphic cells that invade other tissues. "The associations between SMC4 and markers of various immune cells in pan-cancer were detected using GEPIA database." (PMID 36719264, 2023). "We have introduced 1 cancer-specific deletion mutation at the homologous position of SMC4 (i.e., Arg1384*) in diploid yeast and showed that this leads to lethality after sporulation." (PMID 29949571, 2018). "Firstly, SMC2 and SMC4 (i.e. hCAP-E and hCAP-C), the core subunits of human condensin I and condensin II, have been shown to be associated with some malignant tumors." (PMID 29467813, 2018). "CXXC4 levels, along with KPNA4 and SMC4, have been associated with cancer progression." (PMID 34187551, 2021). "In the case of new potential markers, the ZWINT and CONDENSIN I subunits NCAPH, SMC2, and SMC4 all showed similar expression levels displayed by markers in the first circuit, even sharing the same clustering of cancer types." (PMID 40430225, 2025). "DEGs related to SMC4 were mainly involved in pathways in cancer, PI3K-Akt signaling pathway and cell cycle pathway, which indicated that in addition to immune infiltration, there was more pathway associated with SMC4 to explore." (PMID 36719264, 2023). "The prognostic significance of SMC4 in pan-cancer was revealed by GEPIA and Kaplan-Meier Plotter datasets." (PMID 36719264, 2023). "Knockdown of SMC-4 significantly suppressed the proliferation of cancer cells and degraded its malignant degree." (PMID 31615392, 2019). "Interrogation of the Catalogue of Somatic Mutations in Cancer (COSMIC) database revealed that partial deletions of the ATPase domain of human Smc4 have been observed in a number of cancer patients." (PMID 29949571, 2018). "Particularly, the cell cycle and mitotic regulatory genes expression including: CDK2, CDK2AP2, ACTR3, and chromosome structure associated genes like SMC4, INCENP and GNL3L are changed in treated cancer cells." (PMID 30202240, 2018). "Our results illustrated that gene networks of cell cycle progression or cell proliferation (including: CDK2 and SMC4) are affected in both SOX2OT knock downed cancer cells." (PMID 30202240, 2018). "We analyzed the expression level of SMC4 mRNA in various cancers using Oncomine dataset." (PMID 36719264, 2023). "Correlation between SMC4 expression and immune infiltration of pan-cancer using TIMER database." (PMID 36719264, 2023). "Additionally, the prognostic significance of SMC4 in pan-cancer was detected using the Kaplan-Meier Plotter database." (PMID 36719264, 2023). "Additionally, we observed that DEGs between the SMC4 high group and the SMC4 low group were mainly enriched in pathways in cancer, PI3K-Akt signaling pathway and cell cycle pathway from KEGG analysis." (PMID 36719264, 2023). "While DNA mismatch repair plays a central role in the development of drug resistance in TNBC cancer cells, the high expression of SMC4 may lead to long-term effect of chemotherapy." (PMID 31871499, 2019). "The COSMIC database also revealed that human SMC4 is frequently overexpressed in cancers." (PMID 29949571, 2018). "As a result, SMC4 has been suggested as a potentially novel therapeutic target for cancer therapy." (PMID 29467813, 2018). "To further investigate the role of SMC4 in cancer progression, we performed co-immunoprecipitation (Co-IP) coupled mass spectrum (MS) studies in A549 cells to identify proteins that potentially interact with SMC4." (PMID 27687868, 2016). "Therefore, SMC4 may be a useful marker to predict the survival rate and clinical consequences in patients with these cancers." (PMID 36719264, 2023). "Upregulated SMC4 mRNA level could improve the sensitivity of Cdk1 to drive chromatin compaction at mitotic entry and increase the aggressiveness, proliferation, and dedifferentiation of cancer cells." (PMID 31871499, 2019).